ROBO4 (roundabout guidance receptor 4)
Diseases named in the same sentence as ROBO4 in open-access papers (continued):
Sharing a sentence is not in itself a finding about the gene and the disease.
cancer (13 papers, 2008 to 2025). A tumor composed of atypical neoplastic, often pleomorphic cells that invade other tissues. "Dysregulated expression of ROBO4, either upregulation or downregulation, has been importantly associated with angiogenesis sites and in cancer tissues." (PMID 37675802, 2023). "CADM4 was described as a tumor suppressor gene in multiple cancers, including PCa, while Roundabout homolog 4 (ROBO4) is a transmembrane receptor specifically expressed in endothelial cells." (PMID 40136513, 2025). "It has been shown that an antibody-drug conjugate is effective in cancer-bearing mice against mouse Robo4." (PMID 35740295, 2022). "Here, we review the aberrant expression of Robo4 in cancers and summarize its potential roles and corresponding targeting strategies." (PMID 31160487, 2019). "Our immunoblotting analysis was consistent with both overexpression of endogenous ROBO4 in hypervascular 786-O renal KO and SC cancers, but also detectable host organ expression." (PMID 24376772, 2013). "Previous studies have also shown that some cancer cells expressed Robo4." (PMID 35740295, 2022). "For the first dataset, KEGG pathway analysis revealed that the discovered biomarkers are highly associated with pathways including “Wnt signaling pathway WP363” and “Robo4 and VEGF signaling Crosstalk WP3943” which are known to play a role in cancer progression." (PMID 33981841, 2021).
retinopathy (4 papers, 2016 to 2024). "ROBO4-deficient mice show enhanced ocular permeability and revascularization when subjected to oxygen-induced retinopathy, which indicates that ROBO4 plays a role in stabilizing vasculature in ocular pathological conditions." (PMID 32879763, 2020). "Taken together, we propose that Robo4 blockade might represent an opportunity to accelerate revascularization in retinopathy of prematurity and wound healing in diabetic patients." (PMID 27882935, 2016). "Besides lowering inflammation, high miR-146a-5p expression may also affect retinopathy by downregulating the proangiogenic HIF-1α-ROBO4 pathway." (PMID 34823560, 2021).
infection (2 papers, 2011 to 2025). The state of being infected such as from the introduction of a foreign agent such as serum, vaccine, antigenic substance or organism. "They as part of a potential compensatory mechanism aimed at preserving vascular integrity during infection-induced vascular stress, since the inflammatory stimuli, triggered by an infection, can downregulate the SLIT2/ROBO4 axis, leading to increased vascular permeability." (PMID 40124360, 2025).
ROBO4 also shares sentences with these, for which no sentence is quoted: breast carcinoma (3 papers); alopecia (1); aorta (1); aortic aneurysm (1); aortic regurgitation (1); aortic stenosis (1); autosomal recessive nonsyndromic deafness (1); Bicuspid aortic valve (1); brain injury (1); cavernous cerebral malformations (1); Cerebral ischemia (1); diabetic nephropathy (1); ganglioglioma (1); glomerulosclerosis (1); HIV-1 infection (1); infectious disease (1); kidney cancer (1); multiple sclerosis (1); neuroblastoma (1); prostate tumors (1); Pulmonary hypoplasia (1); renal carcinoma (1); renal cell carcinoma (1); retinal disease (1); rheumatoid arthritis (1); systemic sclerosis (1); transient cerebral ischemia (1); type 2 diabetic nephropathy (1); vasculopathies (1).